SMAD3 (SMAD family member 3)
Diseases named in the same sentence as SMAD3 in open-access papers (continued):
Sharing a sentence is not in itself a finding about the gene and the disease.
ovarian carcinoma (continued). "In our study, we found that downregulated expression of ITGB6 could reduce the activation level of the Smad3 pathway when ovarian cancer spheroids were treated with rhTGFβ1." (PMID 34621667, 2021). "In this report, we found that SMYD3 and ITGB6 could promote the release and activation of latent TGFβ1 and increase the phosphorylation of Smad3 activated by TGFβ1 in ovarian cancer spheroids." (PMID 34621667, 2021). "Therefore, SMYD3 and ITGB6 could stimulate the TGFβ1/Smad3 pathway and regulate the expression of N-cadherin, Snail, Vimentin, E-cadherin in ovarian cancer spheroids and promote the EMT process." (PMID 34621667, 2021). "In ovarian cancer, SMAD1 positively regulates SOX2 and SMAD3 negatively regulates SOX2, which acts as a regulatory node that controls the signalling of the TGF-β pathway, which in turn affects ovarian cancer metastasis." (PMID 37685308, 2023). "SMAD3 is a well-acknowledged critical transcription factor in the signaling pathway of TGF-β 36 and also a latent biomarker for ovarian cancer prognosis prediction." (PMID 35342355, 2022). "We cannot exclude the possibility that lncRNA CASC15 promoted ovarian cancer EMT progress and metastasis through means other than the miR-23b-3p/miR-24-3p/SMAD3 pathway." (PMID 35342355, 2022). "In this context, our results described a positive feedback loop of CASC15-SMAD3 in which CASC15 promoted the ovarian cancer EMT program and metastasis by increasing SMAD3 expression; in turn, SMAD3 stimulated the promoter activity of lncRNA CASC15." (PMID 35342355, 2022). "We evaluated the differences in the expression of the YAP, TEAD4, SMAD2, SMAD3, H2A.X, ALD1A1, CD71, TKT, and TKTL1 in ovarian cancers and benign cysts." (PMID 34205023, 2021). "Nonetheless, in ovarian cancer cells, GULP1 showed inhibitory effects on their proliferation while inducing phospho-SMAD3 or reducing phosphorylation of AKT/PDK1 and MAPK." (PMID 34576193, 2021). "In ovarian cancer, the TGF-β-activated SMAD3/SMAD4 complex is recruited to the promoter region of FXYD5 and promotes FXYD5 transcription." (PMID 34270462, 2021). "The H2A.X, CD71, SMAD3 and 4, TKT, and TKTL1 proteins require further studies to confirm their suitability for clinical use in ovarian cancer patients." (PMID 34205023, 2021). "Given that NEDD4L plays an important role in constraining transforming growth factor β signaling by targeting activated Smad2/Smad3 for degradation, we investigated the role of DDB2 in the regulation of TGF-β signaling in ovarian cancer cells." (PMID 26130719, 2015). "To exclude ovarian cancer cell lines with malfunctioned TGF-β signalling, we tested the TGF-β/Smad signalling component, Smad3 and the p21WAF1/CIP1 gene induction under TGF-β treatment for the selected cell lines." (PMID 19755996, 2009). "Smad2/Smad3 represent direct targets of TGF-β receptor kinase 1 and mediate transcriptional regulation through their intrinsic ability to bind to DNA; their phosphorylation plays a crucial role in the pathogenesis of ovarian cancer." (PMID 31666925, 2019). "In ovarian cancer, FoxO3a interacted with a SMAD2/SMAD3/SMAD4 complex in the nucleus, which could maintain activated SMAD proteins at high levels, and this interaction in turn promoted the cell-cycle arrest synergistically." (PMID 31640193, 2019). "Here we show that in mesenchymal-like ovarian cancer cells, the activation and nuclear translocation of Smad3 do not depend on clathrin mediated endocytosis." (PMID 22927969, 2012).
ovarian carcinoma (continued). "Notably, our study found that CASC15 was a TGF-β downstream molecule and involved in the TGF-β/SMAD3 pathway in ovarian cancer: CASC15 was upregulated by TGF-β1, and then increased the expression of SMAD3 via serving as a ceRNA to facilitate cell migration and invasion in ovarian cancer." (PMID 35342355, 2022). "Therefore, it is possible to propound that in ovarian cancer, H2O2 might induce Smad3 phosphorylation at the linker region." (PMID 26091707, 2016). "On the other hand, increased phosphorylated Smad3 at a nuclear location in ovarian cancer cells observed in the present study, does not necessarily indicate that Smad3 could be involved in cell cycle inhibition." (PMID 26091707, 2016). "We found that anti-ITGB6 antibody was more effective in inhibiting the phosphorylation level of Smad3 in 3D-cultured NC-ITGAV cells than in 3D-cultured si-ITGAV cells, implying that ITGAV might play a role in ITGB6-regulated activation of latent TGFβ1 in 3D-cultured ovarian cancer spheroids." (PMID 34621667, 2021). "As downstream targets of the TGFβ1/SMAD3 pathway and essential participants in EMT promotion, N-cadherin, Vimentin, E-cadherin and Snail were found to be regulated by SMYD3 and ITGB6 and could contribute to enhanced invasion and adhesion in ovarian cancer spheroids." (PMID 34621667, 2021). "There was no statistical significance in the expression of mRNA for SMAD3, and borderline statistical significance for SMAD2 between the groups of ovarian cancer patients and other subgroups of patients with simple cysts and healthy ovarian tissue (p = 0.709 and p = 0.053, respectively)." (PMID 34205023, 2021). "There was no statistical significance in the expression of mRNA for SMAD3, and there was borderline statistical significance for SMAD2 between the groups of ovarian cancer patients and other subgroups of patients with simple cysts and healthy ovarian tissue (p = 0.726 and p = 0.046, respectively)." (PMID 34205023, 2021).
cardiac hypertrophy (29 papers, 2012 to 2026). "In this sense, a TGFβ mediator, Smad-3, has been also implicated cardiac hypertrophy, fibrosis, and diastolic dysfunction in T2DM mice." (PMID 28231848, 2017). "Both in vivo and in vitro studies have revealed that TMAO promotes cardiac hypertrophy and fibrosis via the Smad3 signaling pathway." (PMID 41601761, 2026). "Smad3, a protein that is downstream of TGF-β1, forms the TGF-1/Smad3 axis, a crucial target for preventing cardiac hypertrophy." (PMID 37275755, 2023). "Inhibition of the TGF-β1/Smad3 axis suppressed cardiac hypertrophy and suppressed fibroblast-to-myofibroblast transformation." (PMID 36159334, 2022). "Smad3 is a downstream protein of TGF-β1 and constitutes a TGF-β1/Smad3 axis, a potential target in combating cardiac hypertrophy." (PMID 36159334, 2022). "Consistently, in-depth analysis of the affected genes in the significantly enriched pathways revealed that TGF-β1 and Smad3 appeared in multiple signaling pathways, such as cardiac hypertrophy signaling and neuroinflammation signaling pathway." (PMID 34925046, 2021). "In SHR, myocardial hypertrophy and the total quantity and properties of collagen fibres can be improved by affecting the level of Smad3." (PMID 32631115, 2020). "Smad3 KO mice infused with angiotensin II become hypertensive, but develop less cardiac hypertrophy, inflammation, and left ventricular dysfunction than WT mice." (PMID 29073282, 2017). "Transaortic constriction leads to a significant increase in cardiac hypertrophy in the Smad3 knockout mice, indicating a beneficial role of Smad3 by delimiting cardiomyocyte hypertrophic growth." (PMID 22926414, 2012). "Inactivation of the TGF-β1/Smad3 axis could suppress cardiac hypertrophy and suppress the transformation of the fibroblast to myofibroblast." (PMID 37275755, 2023). "Our data speculated that LOXL2 might be a potential contributing factor to Ang II-induced cardiac hypertrophy, and TGF-β1/Smad3/NF-κB is involved in a signal axis and might be a potential strategy in treating cardiac hypertrophy." (PMID 36159334, 2022). "The TMA synthesis inhibitor 3,3-dimethyl-1-butanol (DMB) has been found to prevent cardiac hypertrophy and fibrosis by modulating the transforming growth factor-β1 (TGF-β1)/Smad3 and p65 nuclear factor-κB (NF-κB) signaling pathways." (PMID 41601761, 2026). "Our data suggest that NKT can delay or reverse the progression of HF after AAC and reduce myocardial hypertrophy and fibrosis possibly via inhibition of the TGF-β1/Smad3 signaling pathway." (PMID 41684513, 2026). "Meanwhile, LOXL2 silencing protects against Ang II-induced cardiac hypertrophy via inhibition of the EMT process and down-regulation of the TGF-β1/Smad3/NF-κB pathway." (PMID 36159334, 2022). "We clearly demonstrated that administration of gallic acid prevents cardiac hypertrophy and fibrosis through the regulation of the MAPK signaling pathway and Smad3-mediated collagen type I expression." (PMID 27703224, 2016). "To further determine the functional role of the TGF-β signaling pathway in the inhibitory effect of CARP on cardiac hypertrophy, we measured TGF-β pathway activation by examining the phosphorylation level of Smad3." (PMID 23227174, 2012). "Therefore, our results suggest LOXL2 as a contributing factor for cardiac hypertrophy, thus providing LOXL2 as a therapeutic target for cardiovascular diseases with cardiac hypertrophy and deregulated TGF-β1/Smad3 pathway, including atrial fibrillation." (PMID 36159334, 2022). "The results of the current study are consistent with the notion that cardiac hypertrophy is preceded by sharp upregulation in the mRNA expression levels of profibrotic markers (TGF-β, SMAD-2, SMAD-3, SMAD-4, and NF-κβ) and marked downregulation of antifibrotic SMAD-7 mRNA and let-7b miRNA." (PMID 36030321, 2022).
cardiac hypertrophy (continued). "The expression of TGF-β and p-Smad3 reduced after QYYY treatment, as well as MYH7 and MYH7/MYH6, which demonstrated QYYY granules can downregulate the key genes involved in cardiac fibrosis and cardiac hypertrophy." (PMID 34484396, 2021). "An experimental study proved that transforming growth factor-β1 (TGF-β1) signaling leads to cardiac hypertrophy and fibrosis through a Mothers Against Decapentaplegic Homolog 3 (SMAD3)-dependent manner 20 days after transverse aortic constriction (TAC) in SMAD3−/− and littermate control mice." (PMID 29765562, 2018). "Gallic acid might be a novel therapeutic agent for the prevention of cardiac hypertrophy and fibrosis by regulating the JNK2 and Smad3 signaling pathway." (PMID 27703224, 2016). "Together, these results indicate that the TGF-β/Smad3 signaling pathway, in concert with the ERK MAPK pathway, may play a role in regulating CARP-mediated attenuation of cardiac hypertrophy and fibrosis in response to pressure overload in vivo." (PMID 23227174, 2012). "Moreover, GA, as a main content in BCW, might be a novel therapeutic agent for the prevention of cardiac hypertrophy and fibrosis by regulating the JNK2 and Smad3 signaling pathway." (PMID 34149410, 2021).
aortic aneurysm (28 papers, 2013 to 2026). A ruptured aneurysm located in the wall of the proximal portion of the descending aorta proceeding from the arch of the aorta. "For instance, the SMAD3 gene was reported to cause prenatal agnathia-otocephaly complex in contrast to postnatal aortic aneurysm, cardiac anomalies, cleft palate and micro/retrognathia (Loeys-Dietz syndrome 3, OMIM#613795)." (PMID 35227291, 2022). "Aortic aneurysm and dissection are the main vascular findings, affecting, respectively 67% (104/155) and 29% (39/133) of all patients described with a SMAD3 variant." (PMID 32154675, 2020). "After identification of SMAD3 as an aortic aneurysm disease causing gene, the vascular phenotype of the Smad3 knock‐out mice was studied in more detail." (PMID 29392890, 2018). "SMAD3 gene mutations were initially reported in patients presenting with aortic aneurysms and early-onset osteoarthritis (AOS), now referred to as LDS 3 with mild systemic features of MFS and LDS." (PMID 30037098, 2018). "We identified a novel SMAD3 mutation in a patient with hypoplastic left heart syndrome (HLHS) who developed progressive aortic aneurysm requiring surgical replacement of the neoaortic root, ascending aorta, and proximal aortic arch." (PMID 24711937, 2014). "Taken together, this suggests that disruption of ILK-Pinch1 signaling in NCCs results in reduced Smad3 phosphorylation that ultimately causes the aortic aneurysms phenotype." (PMID 23744273, 2013). "Macrophage depletion and iNOS antagonism represent 2 promising approaches for preventing aortic aneurysms related to SMAD3 mutations and merit further investigation as adjunctive strategies for the life‐threatening manifestations of AOS." (PMID 23782924, 2013). "Because deficient Smad3 signaling in humans results in aortic aneurysms, we propose that NCC differentiation is probably contributing to the aneurysmal CAT phenotype, which is also a common feature in Ilk and Pinch1 mutants." (PMID 23744273, 2013). "In addition to aortic aneurysms, SMAD3 mutations can cause a number of additional vascular manifestations, including intracranial aneurysm, abdominal aortic aneurysm, iliac artery aneurysm, and arterial tortuosity." (PMID 36926042, 2023). "Taken together, these data indicate that SMAD3 deficiency causes pathologic changes in aortic biomechanics as well as functional deterioration and that these changes parallel the characteristic features of connective tissue disorders in aortic aneurysms." (PMID 23782924, 2013). "Based on our in vivo data, iNOS antagonism represents a promising approach to tackling aortic aneurysms related to SMAD3 mutations, and it merits further investigation as an adjunctive strategy for AOS patients to prevent major life‐threatening manifestations of this disorder." (PMID 23782924, 2013). "Using uniaxial tensile and contractility tests, we showed that SMAD3 deficiency resulted in defective aortic biomechanics and physiological functions, which caused weakening of the aortic wall and predisposed the mice to aortic aneurysms." (PMID 23782924, 2013). "Importantly, they also found that 19% of individuals carrying a variant in SMAD3 experienced extra-thoracic disease - abdominal aortic aneurysm, iliac artery aneurysm, or intracranial aneurysm - which argues for screening for other aneurysmal sites in those carrying a SMAD3 variant." (PMID 40337343, 2024). "Additionally, our conditional Ilk mutant mice might prove useful as a model to study aortic aneurysms caused by reduced Smad3 signaling, such as in the new AOS." (PMID 23744273, 2013). "Many genes have been implicated in the etiology of non-syndromic aortic aneurysm such as ACTA2, MYH11, FLNA, and SMAD3." (PMID 38404628, 2023). "This is supported by studies of SMAD3 knockout mice, which experience greatly accelerated development of aortic aneurysms and death." (PMID 36830724, 2023).
aortic aneurysm (continued). "Variants in SMAD3 were previously reported to cause autosomal dominant Loeys-Dietz syndrome 3 (OMIM: 613795), a connective tissue disorder, presenting with aortic aneurysm, cardiac anomalies, cleft palate and significant micro-/retrognathia." (PMID 30679815, 2019). "Smad3−/− mice develop aortic aneurysms rapidly and show intervertebral disc degradation and kyphosis." (PMID 30037098, 2018). "Angiotensin II infusion into Smad3 KO mice on the C57BL/6J background has been used as a model for development of aortic aneurysms and aortic dissections." (PMID 29073282, 2017). "In mice with homozygous deletion of the Smad3 gene, angiotensin II (Ang II) infusion promotes the development of aortic aneurysms and aortic dissection." (PMID 26925344, 2016). "Despite the identification of SMAD3 mutations in human AOS,4–5 the molecular events leading to the pathogenesis of aortic aneurysms in these patients remain elusive." (PMID 23782924, 2013). "For SMAD3, this was not considered to be invalidating because humans with SMAD3 pathogenic variants are known to have aortic aneurysms throughout all three regions of the aorta." (PMID 40066353, 2025). "Loss-of-function mutations or deficiency of SMAD2, SMAD3, and SMAD4 genes in mice or humans lead to the formation of aortic aneurysms or dissections, suggesting that basal TGF-βsignaling canonical signaling is indispensable for maintaining the integrity of aortic structure and function." (PMID 35517795, 2022). "Moreover, the data suggest that disruption of ILK signaling in NCCs leads to aortic aneurysms through a signaling pathway that involves reduced Smad3 signaling." (PMID 23744273, 2013). "However, the etiology and molecular events downstream of SMAD3 leading to the pathogenesis of aortic aneurysms in these patients still remain elusive." (PMID 23782924, 2013). "During our previous studies, we noted that some of Smad3 KO mice on the 129 genetic background died suddenly, but did not develop aortic aneurysms." (PMID 29073282, 2017).